EBPL (EBP like)
Description:
Does not possess sterol isomerase activity and does not bind sigma ligands.
Synonyms: EBRP
Tractability: Small molecule: a high-quality ligand is known; it belongs to a druggable protein family. Antibody: UniProt predicts a signal peptide or a membrane-spanning region. PROTAC: a small molecule that binds it is known.
Gene: Protein-coding gene on chromosome 13 (49,660,674 to 49,691,500, reverse strand). Ensembl gene ENSG00000123179.
Subcellular location: Endoplasmic reticulum membrane
Subcellular location (Human Protein Atlas): Endoplasmic reticulum
Gene Ontology:
Molecular function: cholestenol delta-isomerase activity
Biological process: sterol metabolic process
Cellular component: endoplasmic reticulum; endoplasmic reticulum membrane; membrane
Genetic constraint (gnomAD): Loss-of-function variants: 24 observed, 23.9 expected, observed/expected ratio (o/e) 1, 90% interval 0.73 to 1.41. The upper end of that interval is the gene's LOEUF score, 1.41, which puts it in group 5 of 6, group 1 being the genes least tolerant of losing a copy. Missense variants: 219 observed, 221.2 expected, observed/expected ratio (o/e) 0.99, 90% interval 0.89 to 1.11. Synonymous variants: 107 observed, 97.33 expected, observed/expected ratio (o/e) 1.1, 90% interval 0.94 to 1.29.
Homologues: Orthologues: chimpanzee EBPL (99% identical), macaque EBPL (97% identical), pig EBPL (80% identical), rat Ebpl (77% identical), mouse Ebpl (76% identical), tropical clawed frog ebpl (67% identical), zebrafish ebpl (63% identical), guinea pig EBPL (60% identical), dog EBPL (57% identical). Paralogues in human: EBP (26% identical).
Diseases named in the same sentence as EBPL in open-access papers:
EBPL is named in the same sentence as 8 diseases in open-access papers, as found by Europe PMC text mining. Sharing a sentence is not in itself a finding about the gene and the disease. The quoted sentences say what the papers report.
Hepatic steatosis (1 paper, 2025). Steatosis is a term used to denote lipid accumulation within hepatocytes. "In addition, recent studies have implicated HNF4A and PROX1-AS1 in insulin resistance and T2D, whereas loci harboring FAM13A, RSPO3, and EBPL have been associated with body fat distribution and hepatic steatosis." (PMID 39796632, 2025).
hepatocellular carcinoma (1 paper, 2020). A malignant tumor that arises from hepatocytes. "The results showed that EBP-like expression level was significantly increased with the treatment of 17β-estradiol in chicken hepatocellular carcinoma cells and in chicken liver tissue." (PMID 33519893, 2020).
leukemia (1 paper, 2021). A malignant (clonal) hematologic disorder, involving hematopoietic stem cells and characterized by the presence of primitive or atypical myeloid or lymphoid cells in the bone marrow and the blood. "In addition, we identified genes of previously unknown cancer relevance with regards to leukemia circulation (e.g., LRIF1, DNAJC1, and CMC2) and therapeutic treatment (e.g., EBPL, MESDC2, ZRANB2, GTF2A2)." (PMID 34764253, 2021).
prostate carcinoma (1 paper, 2020). A carcinoma that arises from epithelial cells of the prostate gland. "In our TWAS of prostate cancer across African Americans, we report EBPL as a gene significantly associated (lfsr = 0.0423) with prostate cancer in this population." (PMID 32986714, 2020).
EBPL also shares sentences with these, for which no sentence is quoted: cancer (1 paper); Insulin resistance (1); liposarcoma (1); liver cancer (1).